CXCR4 (C-X-C motif chemokine receptor 4)
Diseases named in the same sentence as CXCR4 in open-access papers (continued):
Sharing a sentence is not in itself a finding about the gene and the disease.
tumor (continued). "The mechanism of tumor proliferation is a multi-step process involving several factors and pathways, including the CXCL12/CXCR4 axis." (PMID 40142155, 2025). "This echoes the findings from preclinical models showing that tumor microenvironment therapeutic reprogramming via CXCR4 blockade, CD40 agonists, or TGF-β inhibition enhances Tc recruitment and restores anti-tumor activity." (PMID 41375696, 2025). "CXCR4-expressing CD90 + cells demonstrated enhanced migration towards sites of inflammation, tissue injury, or tumours, facilitating T-cell recruitment and activation and thereby promoting tissue repair, regeneration, and antitumor immunity." (PMID 41243106, 2025). "Disruption of this axis using CXCR4 inhibitors, such as AMD3100, can mitigate tumor progression to some extent." (PMID 40698080, 2025). "The rationale behind this combination strategy relates to the involvement of CXCR4 and its ligand CXCL12 in supporting tumor cell growth and angiogenesis, as well as immunosuppression in the tumor microenvironment." (PMID 40918456, 2025). "The most significant issue is tumour heterogeneity, as TNBC is a diverse disease with many molecular subtypes that exhibit variable levels of CXCR4 expression and reliance on CXCR4-mediated signalling." (PMID 41002447, 2025). "We found that the signaling of VEGFA-VEGFR1, VEGFA-VEGFR2, MIF-(CD74 + CXCR4) and MIF-(CD74 + CD44) was significantly increased in the high-risk state; whereas the signaling of LGALS9-CD45, LGALS9-CD44, and IL1B-IL1R2 was decreased, which may affect the tumor cell adhesion and migration." (PMID 40563096, 2025). "Future studies will however be required to explore the role of these receptors in vivo to understand the intricacies of each function orchestrated by CXCR4 and S1PR5 in tumor-infiltrating NK cells." (PMID 40155684, 2025). "Blocking CXCR4 allows for reducing the crosstalk between the TME and tumor cells, which leads to the inhibition of tumor metastasis." (PMID 41550883, 2025). "Subsequent CellChat analysis revealed enhanced interactions between ACACA-high tumor cells and CD8+ T cells, primarily via secreted signaling pathways like the macrophage migration inhibitory factor (MIF) axis (MIF-CD74+CXCR4, MIF-(CD274+CD44))." (PMID 41169354, 2025). "CXCR4, a protein found on tumor cells, binds to its receptor CXCL12, presents on bone marrow stromal cells, and induces tumor cell migration to bone." (PMID 38474093, 2024). "CXCL12 influences tumor progression through interactions with its 2 receptors, CXCR4 and ACKR3, especially CXCR4." (PMID 39545420, 2024). "CXCR4 and CXCR5 were also more highly expressed in tumor-rich tissues than in circulating T cells, but only in CD8+ T cells." (PMID 38335302, 2024). "Disrupting this axis using CXCR4 antagonists or neutralizing antibodies can reduce CSC properties and tumor growth." (PMID 39519109, 2024). "The present study examined CXCR4, JUNB, and PD-L1 at molecular and protein levels in circulating tumor cells (CTCs) derived from patients with mPCa." (PMID 38727318, 2024). "The MDA-MB-231 tumor-bearing mice were randomly divided into four groups, which were treated by PBS only, anti-CXCR4-peptide, Try-NaGdF4 NDs and anti-CXCR4-NaGdF4 NDs, respectively." (PMID 38982161, 2024). "CXCR4, a member of the G protein-coupled receptor (GPCR) family, controls a range of cellular functions, such as tumor cell migration, proliferation, and survival." (PMID 38502348, 2024). "In naive cells, critical pathways such as MIF-CD74/CXCR4, MDK-SDC1, and HLA-E-CD8A were predominant, playing pivotal roles in immune modulation and tumor cell survival." (PMID 39850495, 2024). "Bidirectional crosstalk between tumor cells and CAFs enhances the ability of fibroblasts to secrete various pro-tumor chemokines, including CXCL12/CXCR4 axis, CCL2, CCL5, CCL7, CXCL8, and CXCL14." (PMID 39092186, 2024).
tumor (continued). "CXCR4 promotes VEGF expression, the mitosis and proliferation of vascular endothelial cells, and the tumor to generate new vessels." (PMID 38454277, 2024). "We found that the adoptive transfer of CXCR4+ B cells combined with CXCL12 effectively inhibited HCC progression and prolonged the survival time of tumor‐bearing mice." (PMID 39422063, 2024). "CXCR4-PEG-CdTe-DOX can proactively target CXCR4 antigen on the surface of U266 cells, and can effectively transport DOX to tumor cells." (PMID 38244066, 2024). "C-X-C chemokine receptor type 4 (CXCR4), a chemokine receptor overexpressed in >75% of cancers, is crucial for tumor cell proliferation, dissemination, and angiogenesis." (PMID 38617537, 2024). "The endocrine signals of the tumor microenvironment influence the migration of MSCs, including mainly the regulatory signal produced by SDF-1/CXCR4." (PMID 38607056, 2024). "The reciprocal modulation between the CXCL12/CXCR4/ACKR3 axis and the STAT3 signaling pathway plays a crucial role in the progression of various diseases and neoplasms." (PMID 38920657, 2024). "Patients with high CCR5, CCR7, CXCR4, and CXCR5 expression on tumors and high CXCR4 expression on tumor-infiltrating lymphocytes were less likely to have a chemotherapy response compared to others." (PMID 39001456, 2024). "Directional migration and invasiveness of tumor cells is enhanced by the CXCL12/HMGB1 heterocomplex, and is CXCR4 dependent." (PMID 38803493, 2024). "Stachydrine impedes the migration and invasive capabilities of tumor cells by inhibiting signaling pathways such as CXCR4/ERK and CXCR4/Akt." (PMID 39170783, 2024). "The chemokine receptors CXCR4, CXCR6, CCR1, CCR7 and CCR9 also play an important role in the homing of MSCs to tumours." (PMID 39062449, 2024). "Crucially, MDSCs are recruited to tumor sites via various chemokine axes, such as CCL8/CCR2, CCL5/CCR5, CXCL5/CXCR2, and CXCL12/CXCR4." (PMID 39769501, 2024). "The CXCL12/CXCR4/ACKR3 signaling axis activates the STAT3 pathway, playing a central role in tumor proliferation, metastasis, anti-apoptosis, maintenance of tumor stemness, and immune escape." (PMID 38920657, 2024). "MDM2 and MDMX promote circulating tumor cell (CTC) formation and metastasis, and positively correlate with a high expression of CXCR4." (PMID 39766093, 2024). "Diffuse CXCR4 signal in the LV was increased in both groups, anti-PD-L1 and isotype Ctrl treatment, after GCV-mediated tumor elimination, on day 35, but to a lesser extent in anti-PD-L1-treated animals." (PMID 39834851, 2024). "The present study unravels distinct therapeutic properties of taxol-treated MSC-derived exosomes with the expression of predominant anti-tumor miR patterns and increased tumor tropism via an elevated SDF-1/CXCR4/CXCR7 axis." (PMID 39420354, 2024). "Blocking CXCR4 function reduces GSC invasiveness and tumor growth, suggesting its potential as a therapeutic target for limiting GBM spread." (PMID 39063221, 2024). "Recent data have shown that a combination approach of drugs targeting the function of CXCR4 and PD-L1 enhances the efficacy of anti-PD-L1 therapy in TNBC by preventing two important signaling pathways of tumor proliferation." (PMID 38727318, 2024). "CircFGFR1 activates its downstream gene C-X-C motif chemokine receptor 4 (CXCR4) through spongy adsorption of miR-381-3p, promoting tumor malignant progression and anti-PD-1 immunotherapy resistance." (PMID 38177102, 2024). "Highly involved in tumor progression and metastasis from previous research, CXCL12/CXCR4 axis is regarded as one promising therapeutic target in cancer." (PMID 38833154, 2024). "Mechanistic insights reveal that tumor-infiltrating Tc17 cells induce tumor cells to produce CXCL12, promoting the migration of MDSCs to the TME in a CXCR4-dependent manner." (PMID 39906741, 2024). "Among all subsets, E02-tip-CXCR4 and E06-veins-SELE exhibited the highest degree of enrichment in tumors and non-tumor tissues, respectively." (PMID 39345334, 2024).
tumor (continued). "CXCR4, activated by its ligand CXCL12 (also known as SDF-1), plays a crucial role in promoting the migration and invasion of tumor cells in pancreatic ductal adenocarcinoma (PDAC)." (PMID 39001498, 2024). "Increased expression of CD44, CXCR4 and CD74 on group 1 and 2 NK cells, on which numerous signals from fibroblasts, endothelial cells, tumor cells and macrophages converged (COLLAGEN, MIF, LAMININ), facilitated the augmented incoming signaling in NSCLC." (PMID 38956379, 2024). "Activation of CXCR4 on tumor cells stimulates ICAM-1, enhancing their adhesion to endothelial cells, while CXCR4 on immune cells suppresses the intratumoral immune reaction." (PMID 39199569, 2024). "Therefore, we envision CXCR4 antagonism might also benefit PDT for better tumor eradication." (PMID 38553476, 2024). "Furthermore, AMD3100 treatment in an in vivo model of estrogen receptor-positive breast cancer reversed tamoxifen resistance, indicating that the combination of anti-CXCR4 with endocrine therapy could be a more efficient approach for the treatment of this type of tumor." (PMID 39596815, 2024). "The features of anti-CXCR4-NaGdF4 NDs improve the tumor-MRI sensitivity and facilitate tumor biotherapy after injection in mouse-bearing MDA-MB-231 tumor model in vivo." (PMID 38982161, 2024). "Previous studies on CXCR4/CXCL12 signaling demonstrated that the interplay between CAFs and tumor cells played a critical role in tumor progression." (PMID 38587644, 2024). "Despite these two rather unfavorable aspects regarding the practicability of CXCR4-RLT in solid tumors, one has to consider that a substantial portion of patients were diagnosed with difficult-to-treat tumor entities, including ACC." (PMID 38082196, 2024). "The CAFs, recruited to the tumor site by TGF-beta and CXCR4/CXCL12 signaling, enhance cancer cell proliferation and polarize adaptive and innate immune cells toward a tumor-promoting phenotype (also conferring immunotherapy resistance)." (PMID 39950103, 2024). "The authors also mentioned the relationship between CXCR4 and CXCL12 as a potential new target to prevent tumor angiogenesis in PCa." (PMID 38745115, 2024). "The mobilization of dormant tumor cells from the PVN to the peripheral blood is mediated by C-X-C motif chemokine Receptor 4 (CXCR4) inhibition, suggesting that the axis CXCR4/CXCL12 (CXC motif chemokine 12) is crucial to anchor dormant tumor cells in the PVN." (PMID 39682261, 2024). "We therefore investigated CXCR4 expression in the stroma of OSCC from the perspective of oral pathology, focusing on the abundance of CXCR4-positive tumor blood vessels." (PMID 39001388, 2024). "Previous studies have suggested that SDF-1 can perform receptor-mediated interactions e.g. by binding to its specific receptors CXCR4 and CXCR7 on cancer cells, thereby contributing to cancer cell proliferation, angiogenesis, invasion, and tumor metastasis." (PMID 39420354, 2024). "In vivo therapeutic efficacy was longitudinally monitored using serial 18F-FDG, [18F]AlF-NOTA-FAPI-04, and [68Ga]Ga-DOTA-Pentixafor PET/CT scans and validated using tumor sections through immunohistochemical staining of Ki-67, α-SMA, CXCR4, and CXCL12." (PMID 38587644, 2024). "Other anti-CXCR4 antibodies include LY2624587, hz515H7 (F-50067), and MEDI3185, which exhibit anti-tumor activity in hematological malignancies in mice." (PMID 38612911, 2024). "Our approach provided a significant number of genes related to T cell function in the tumor microenvironment, including HSP90AA1, ETS1, CXCR4, RGS1, and FYN, all detected at the gene level." (PMID 39548591, 2024). "CXCR4+ macrophages participate in the process of extracellular matrix remodeling and promote tumor proliferation and migration in a murine orthotopic PDAC model through SPARC secretion via the CXCR4/PI3K/Akt pathway." (PMID 39494816, 2024).
tumor (continued). "Their study showed that blocking CXCR4 function reduces GSC invasiveness and tumor growth, suggesting its potential as a therapeutic target to limit GBM spread." (PMID 39063221, 2024). "The expression of the receptors CXCR4 and CD74 was markedly increased in tumor cells, suggesting activation of the MIF signaling pathway in tumors." (PMID 38191424, 2024). "The interaction between CXCR4 and CXCL12 promotes the migration of tumour cells, their invasion into surrounding tissues, and the formation of new metastases." (PMID 38474372, 2024). "A similar peptide CXCR4 antagonist, CTCE-9908, significantly reduced the tumor burden in MDA-MB-231 breast cancer tumor-bearing mice and displayed a 20-fold reduction in metastasis compared to control." (PMID 38612911, 2024). "C-X-C chemokine receptor type 4 (CXCR4), expressed on cancer cells, binds to CXCL12 and promotes tumor growth." (PMID 39404428, 2024). "Studies have shown that celastrol decreases CXCR4 expression in a dose-dependent manner and downregulates related downstream pathways, including the PI3K/AKT pathway, significantly reducing tumor cell proliferation and migration capacity 54-55." (PMID 39494324, 2024). "They combined cell experiments and found that CXCR4 antagonist AMD3100 can effectively inhibit the proliferation and migration of tumor endothelial cells." (PMID 39470950, 2024). "The proteins CAPS3, ICAM-1, CXCR4, and PTGS2 are key players in regulating the life cycles of tumor cells." (PMID 38502348, 2024). "There was a marked upregulation of CXCR4 and FAP in the tumor tissues of TNBC patients, suggesting that they promote tumor progression in a concerted manner." (PMID 38587644, 2024). "Further, curcumin downregulated the gene expression of factors secreted by tumor cells known to induce immunosuppression (VEGFA, PDGF, IL4, OSM, CXCR4 and Fas ligand)." (PMID 39861845, 2024). "It was previously demonstrated that CXCR4 expression favored EMT and accelerated tumor growth in vivo with CXCR4 inhibition affecting the EMT markers." (PMID 39700131, 2024). "The authors demonstrated that the ligand, CXCL12, stimulated the CXCR4-expressing TNBC cell line, MDAMB-231, and led to an increase in the chemotaxis and chemoinvasion of tumor cells toward its ligand." (PMID 39001456, 2024). "Both in vitro and in vivo experimental results indicate that the as-prepared anti-CXCR4-NaGdF4 NDs exhibit high MRI enhancing performance, good MDA-MB-231 tumor suppression capacity and low toxicity in vivo." (PMID 38982161, 2024). "Activation of downstream CXCR4 signaling by CAF-derived CXCL12 promotes EMT and contributes to tumor stem cell activity." (PMID 39092186, 2024). "We also observed colocalization of CXCL12+ fibroblasts with CXCR4+ CK17+ single tumor cells in the subcapsular sinus, the initial site of disseminated tumor cell arrival." (PMID 39236316, 2024). "Consistent with a case report describing tumor cells in a patient with skin-related EMM, we observed decreased expression of CXCR4, the protein product of which is responsible for the normal homing of PCs to BM." (PMID 38493239, 2024). "The disruption of CXCR4/CXCL12 signaling can enhance the efficacy of chemotherapy and immunotherapy by blunting the migration and metastasis of tumor cells and remodeling of the immunosuppressive tumor microenvironment (TME)." (PMID 38587644, 2024). "Paired PBMC and tissue samples from patients undergoing tumor resection were analyzed by flow cytometry to assess tissue entry and compare phenotype and developmental potential of Lin-CD34+DNAM-1bright CXCR4+ cells in both compartments." (PMID 38390333, 2024). "In brief, chemokine signaling is crucial for tumor angiogenesis (CXCR2 and CXCR4), immunosuppression (CXCR3 and CCR2), and tumor progression and metastasis (CCR5 and CXCR6)." (PMID 39456552, 2024).
tumor (continued). "Moreover, iCAFs could specifically generate CXCL12 to interact with tumor-infiltrating myeloid cells through the activation of the CXCL12/CXCR4 axis to induce the M2 polarization of macrophages or restrain the antigen presentation of cDCs to suppress antitumor immunity." (PMID 39323622, 2024). "(iii) Studying CXCR4 expression patterns can deepen our understanding of GBM heterogeneity and its implications for tumor behavior and treatment outcomes." (PMID 39162901, 2024). "Through complex interactions with molecules such as DARPP-32, STAT-3, CXCR4, and CXCL-12, dopamine contributes to cancer cell invasion, immune response modulation, and tumor growth by stabilizing key proteins involved in angiogenesis and metastasis." (PMID 39767693, 2024). "MIF-(CD74+CXCR4) and MIF-(CD74+CC44) interactions happened in dendritic cells, M1 macrophage, M2 macrophage, monocyte, and plasma cells both in tumor and normal tissues." (PMID 37335089, 2023). "The blockade of the C-X-C chemokine receptor type 4 (CXCR4) pathway by balixafortide played a crucial role in inhibiting metastasis and diffusion, making tumor cells sensitive to chemotherapy, and activating the immune system in the TME." (PMID 38298540, 2023). "In contrast, upregulated levels of angiogenic chemokine SDF-1 and subsequent binding to CXCR4, the cognate receptor for SDF-1, can induce angiogenesis and promote tumor progression." (PMID 38067195, 2023). "Targeting CXCR4 or CXCR2 can reduce MDSCs infiltration, which contributes to the inhibition of tumor growth and metastasis." (PMID 37350962, 2023). "Tumor cells produce multiple chemokines, including large amounts of CXCL12, which recruits pDCs by binding CXCR4 on pDCs in oral squamous cell carcinoma." (PMID 37817484, 2023). "The following mechanism was: cGAMP stimulated innate and adaptive immunity, changed the tumour immune milieu, down-regulated the expression of M2-TAM and TGF-β and impaired the combining capacity of CXCR4 and CXCL12." (PMID 37162544, 2023). "NK cells modified to express CXCR2, CXCR4, CCR5, or CCR7 have all been shown to have enhanced tumor control in mice." (PMID 37205115, 2023). "68Ga-Pentixafor as radio ligand for CXCR4 has been proven an alternative to 18F-FDG PET, showing clearly higher detection rates and better tumor-to-background contrast." (PMID 37614665, 2023). "For example, EVs’ FLT3-ITD and NPM1 mRNAs serve for determining AML prognosis; FLT3-ITD, IGF-IR, and CXCR4 mRNAs help in AML treatment, whereas IGF-IR, CXCR4, and MMP4 mRNAs aid in understanding the behavior of the tumor niche." (PMID 37371477, 2023). "Further, univariate analysis of LUAD patients revealed that OS was significantly correlated with age, tumor length, differentiation, T stage, lymph node metastasis, TNM stage, and CXCR4 expression (P < 0.05)." (PMID 36308553, 2023). "The CXCR4 and CCR2 expressed on UMSCs can interact with overexpressed SDF-1α and MCP-1 in GBM40–42, thus providing tumor-homing tropism." (PMID 36650171, 2023). "In the analysis of L/R pairs, the L/R pairs of MIF/(CD74 + CD44 or + CXCR4) and APP/CD74 were the most prominent interactions involving signal transduction from tumor cells to PCs." (PMID 37138324, 2023). "Its functional receptor, CXCR4, is highly expressed in various human malignancies, and numerous studies have shown that the CXCL12/CXCR4 axis promotes tumor growth, angiogenesis, invasion, and metastasis." (PMID 36300800, 2023). "As with the results obtained with IL-18 and PD-1 co-blocking treatment, combining PD-1 and CXCR4 blocking increased CD8+ T-cell infiltration of the tumors and enhanced the survival of the tumor-bearing mice." (PMID 37176035, 2023). "Both mRNA and miR approaches confirmed previous knowledge about the impact of CXCR4 and FAP on tumor microenvironment." (PMID 36672341, 2023).